NAA50 (N-alpha-acetyltransferase 50, NatE catalytic subunit)
Description:
N-alpha-acetyltransferase that acetylates the N-terminus of proteins that retain their initiating methionine. Has a broad substrate specificity: able to acetylate the initiator methionine of most peptides, except for those with a proline in second position. Also displays N-epsilon-acetyltransferase activity by mediating acetylation of the side chain of specific lysines on proteins. Autoacetylates in vivo. The relevance of N-epsilon-acetyltransferase activity is however unclear: able to acetylate H4 in vitro, but this result has not been confirmed in vivo. Component of N-alpha-acetyltransferase complexes containing NAA10 and NAA15, which has N-alpha-acetyltransferase activity. Does not influence the acetyltransferase activity of NAA10. However, it negatively regulates the N-alpha-acetyltransferase activity of the N-terminal acetyltransferase A complex (also called the NatA complex). The multiprotein complexes probably constitute the major contributor for N-terminal acetylation at the ribosome exit tunnel, with NAA10 acetylating all amino termini that are devoid of methionine and NAA50 acetylating other peptides. Required for sister chromatid cohesion during mitosis by promoting binding of CDCA5/sororin to cohesin: may act by counteracting the function of NAA10.
Synonyms: hNaa50p; MAK3; NAT13; NAT5; FLJ13194; San; NAT13P; NAT5P
Tractability: Small molecule: a structure with a bound ligand is known; a high-quality ligand is known; it has a high-quality binding pocket. PROTAC: ubiquitination databases record sites on it; its protein half-life has been measured; a small molecule that binds it is known.
Target class: Enzyme; Transferase
Gene: Protein-coding gene on chromosome 3 (113,716,458 to 113,746,786, reverse strand). Ensembl gene ENSG00000121579.
Subcellular location: Cytoplasm; Nucleus
Subcellular location (Human Protein Atlas): Nucleoli
Gene Ontology:
Molecular function: histone H4 acetyltransferase activity; protein binding; protein-lysine-acetyltransferase activity; protein-N-terminal amino-acid acetyltransferase activity; acyltransferase activity, transferring groups other than amino-acyl groups; protein N-terminal-methionine acetyltransferase activity
Biological process: establishment of mitotic sister chromatid cohesion; mitotic sister chromatid cohesion, centromeric; N-terminal protein amino acid acetylation; mitotic sister chromatid cohesion; chromatin remodeling; post-translational protein modification
Cellular component: cytoplasm; cytosol; extracellular exosome; NatA complex; nucleolus; nucleus
Genetic constraint (gnomAD): Loss-of-function variants: 7 observed, 17.2 expected, observed/expected ratio (o/e) 0.41, 90% interval 0.23 to 0.76. The upper end of that interval is the gene's LOEUF score, 0.76, which puts it in group 3 of 6, group 1 being the genes least tolerant of losing a copy. Missense variants: 103 observed, 184.21 expected, observed/expected ratio (o/e) 0.56, 90% interval 0.48 to 0.66. Synonymous variants: 51 observed, 67.43 expected, observed/expected ratio (o/e) 0.76, 90% interval 0.6 to 0.95.
Homologues: Orthologues: chimpanzee NAA50 (100% identical), dog NAA50 (100% identical), guinea pig NAA50 (99% identical), macaque NAA50 (99% identical), pig NAA50 (99% identical), rabbit NAA50 (98% identical), mouse Naa50 (98% identical), rat Naa50 (96% identical), tropical clawed frog naa50 (96% identical), zebrafish naa50 (92% identical), Drosophila melanogaster san (72% identical), Caenorhabditis elegans F40F4.7 (46% identical). Paralogues in human: NAA10 (25% identical), NAA11 (23% identical), NAA30 (21% identical), NAA20 (19% identical).
Diseases named in the same sentence as NAA50 in open-access papers:
NAA50 is named in the same sentence as 8 diseases in open-access papers, as found by Europe PMC text mining. Sharing a sentence is not in itself a finding about the gene and the disease. The quoted sentences say what the papers report.
Infertility (1 paper, 2022). "From this time point on, naa50 is severely growth retarded and displays premature leaf senescence, defective root cell patterning and infertility." (PMID 36430970, 2022). "In Arabidopsis thaliana, the knockout of NAA50 (AT5G11340) results in severe dwarfism and infertility." (PMID 36430970, 2022).
cancer (3 papers, 2011 to 2022). A tumor composed of atypical neoplastic, often pleomorphic cells that invade other tissues. "Firstly, in order to explore the expression of NAA50 in human cancer, we used the TIMER2.0 database to detect the expression of NAA50." (PMID 36568377, 2022). "In this study, only the role of NAA50 from different databases in pan-cancer was analyzed by bioinformatics and verified by functional experiments, so further in vivo experimental validation and mechanism study are needed." (PMID 36568377, 2022). "In summary, our pan-cancer analysis of NAA50 was conducive to understand the function of NAA50 in tumorigenesis and development from different angles, especially in LUAD." (PMID 36568377, 2022). "However, the functional and prognostic roles of NAA50 in cancers remain unknown and elusive." (PMID 36568377, 2022).
NAA50 also shares sentences with these, for which no sentence is quoted: tumor (2 papers); anhidrosis (1); genetic disease (1); hereditary spastic paraplegia (1); neuroblastoma (1); Riley-Day syndrome (1).